XRCC1 (X-ray repair cross complementing 1)
Diseases named in the same sentence as XRCC1 in open-access papers (continued):
Sharing a sentence is not in itself a finding about the gene and the disease.
atherosclerosis (2 papers, 2015 to 2016). A disease characterized by the build-up of fatty material and calcium deposition in the arterial wall resulting in partial or complete occlusion of the arterial lumen. "Furthermore, polymorphisms in the XRCC1 gene affect DNA repair efficiency and therefore, may influence individual susceptibility to both atherosclerosis and CAD." (PMID 27870881, 2016).
Brain tumors (2 papers, 2020 to 2024). "Likewise, haploinsufficiency in XRCC1 enhances formation of precancerous lesions, and selective depletion of neural XRCC1 or Ape1, another BER component, leads to the development of brain tumours in mice." (PMID 32228693, 2020).
cervical squamous cell carcinoma (2 papers, 2021 to 2024). A squamous cell carcinoma arising from the cervical epithelium. "Furthermore, analysis of DSS prognosis showed the relevance of higher XRCC1 gene expression levels to worse DSS in patients with cervical squamous cell carcinoma and endocervical adenocarcinoma (CESC) (P=0.0015), COAD (P=0.0268), KIRC (P=0.0296), LIHC (P=0.0086) and LUSC (P=0.0190)." (PMID 38217545, 2024).
chronic hepatitis C (2 papers, 2018 to 2020). "The aim of the present study is to investigate the potential association of XRCC1 genetic polymorphisms (c.1254 C > T and c.1517 G > C) with the development of insulin resistance in a sample of chronic hepatitis C Egyptian patients." (PMID 30366460, 2018). "The first objective of our study is to investigate the possible association of XRCC1 genetic polymorphisms (c.1254 C > T and c.1517 G > C) with the development of insulin resistance in a sample of chronic hepatitis C Egyptian patients." (PMID 30366460, 2018). "to investigate the association between XRCC1 gene polymorphism and HCC in Egyptian chronic hepatitis C patients." (PMID 32334466, 2020).
clear cell renal cell carcinoma (2 papers, 2017 to 2024). "This study explored the clinical significance of XRCC1 in human clear cell renal cell carcinoma (ccRCC) and further examined the mechanism of the role of XRCC1 in ccRCC." (PMID 29312615, 2017).
Erythema (2 papers, 2011 to 2012). Redness of the skin, caused by hyperemia of the capillaries in the lower layers of the skin. "While, the association between the polymorphic variant mut/het of XRCC1 Arg194Trp or wt of GSTA1 results in a higher risk of erythema (OR = 6.01; 95% CI, 1.16-61.04)." (PMID 21749698, 2011). "Further, the association of erythema with the presence of a mut/het of XRCC1 Arg194Trp or mut/het of GSTP1 was also found to be statistically significant indicating the protective role of these polymorphisms." (PMID 21749698, 2011). "We found a significant incidence of erythema rate in patients with the polymorphic variant (AA i.e. wt) of XRCC1 Arg194Trp with greater odds (OR = 8.07; 95% CI, 1.02-373.8)." (PMID 21749698, 2011). "The presence of the polymorphic variant mut/het of XRCC1 Arg194Trp or wt of XRCC1 Arg399Gln showed evidence of a protective role towards erythema." (PMID 21749698, 2011). "Our results show a level that is not statistically significant in the protection towards developing an erythema, i.e. lower odds (OR = 0.3; 95% CI, 0.08-1.08), in the presence of at least one allelic variant (mut/het i.e. aa/Aa) of XRCC1 Arg194Trp or of GSTP1 (Ile105Val)." (PMID 21749698, 2011). "Furthermore, the association between the polymorphic variant mut/het of XRCC1 Arg194Trp and the wt of XRCC1 Arg399Gln shows a protective role towards erythema (OR = 0.39; 95% CI: 0.1-1.35)." (PMID 21749698, 2011). "The presence of the polymorphic variant mut/het of XRCC1 Arg194Trp and wt of XRCC3 Thr241Met results significantly in the protection towards developing an erythema with lower odds (OR = 0.2; 95% CI: 0.04-0.78)." (PMID 21749698, 2011). "In addition, a high rate of erythema was correlated with the mut/het of XRCC1 Arg194Trp or with of the wt GSTA1, while a trend toward having a protective factor was observed when a mut/het of XRCC1 Arg194Trp or the wt XRCC1 Arg399Gln alleles were expressed." (PMID 21749698, 2011). "In the present study, a correlation was also found between the absence of erythema and the presence of a mut/het of XRCC1 Arg194Trp or of the wt XRCC3 Thr241Met, indicating the protective role of these alleles." (PMID 21749698, 2011). "In addition, when identifying the low and high risk groups, according to the absence or presence of mut/het XRCC1 Arg194Trp or wt XRCC3 Thr241Met, the observed erythema in our cohort was 20% and 59%, respectively." (PMID 21749698, 2011).
esophageal adenocarcinoma (2 papers, 2011 to 2015). A malignant tumor with glandular differentiation arising predominantly from Barrett mucosa in the lower third of the esophagus. "Assessed for the first time in a prospective, interventional trial cohort of esophageal adenocarcinoma, XRCC1 399Gln was associated with resistance to radiochemotherapy." (PMID 21586140, 2011).
esophagitis (2 papers, 2022 to 2024). An acute or chronic inflammatory disease affecting the esophageal wall. "SNPs in DNA repair-associated XRCC5 (rs3835) and XRCC1 (rs25487) were associated with an increased risk of high-grade esophagitis and pneumonitis, respectively." (PMID 38255239, 2024). "SNPs in the DNA repair-associated XRCC5 (rs3835) and XRCC1 (rs25487) were associated with an increased risk of high-grade esophagitis and pneumonitis respectively." (PMID 35912186, 2022).
Fanconi anemia (2 papers, 2014 to 2020). Fanconi anemia (FA) is a hereditary DNA repair disorder characterized by progressive pancytopenia with bone marrow failure, variable congenital malformations and predisposition to develop hematological or solid tumors. "This is also coincided with the diminished levels of excision repair protein (XRCC1), replication checkpoint kinase protein 1 (Chk1) and other replication stress associated Fanconi anemia (FA)-BRCA gene products FANCD2 and FANCJ." (PMID 25216266, 2014).
fibrosis (2 papers, 2007 to 2020). the formation of excess fibrous connective tissue in an organ or tissue in a reparative or reactive process. "As compared to the no fibrosis group, the cirrhotic group harbored a higher frequency of ERCC2 rs238406 G allele, which appeared to be a risk factor for cirrhosis, and lower numbers of the variant XRCC1 rs25487 C allele, which had a protective effect." (PMID 33171788, 2020). "Three genetic variations (ERCC2: rs238406, XRCC1: rs25487, NBN: rs2735383) had diverse frequency in CHB patients with liver cirrhosis and with no fibrosis, highlighting their possible role in HBV-induced liver disease progression." (PMID 33171788, 2020). "Moreover, for rs238406 (ERCC2), rs25487 (XRCC1), and rs2735383 (NBN), we also found significant differences in genotypic distribution between the liver cirrhosis and no fibrosis group." (PMID 33171788, 2020).
gastric cardia carcinoma (2 papers, 2013 to 2021). A carcinoma that arises from epithelial cells of the cardia of stomach. "In addition, recent studies reported that a series of gene mutation such as adenosine diphosphate ribosyltransferase (ADPRT) and X-ray repair cross-complementing 1 (XRCC1), matrix metalloproteinases 2 (MMP-2), and cyclooxygenase-2 (COX-2) were only associated with the gastric cardia cancer." (PMID 23826241, 2013).
hearing loss (2 papers, 2016 to 2022). "Mutations that occur in base excision repair genes (i.e., hOGG1 and XRCC1) may affect the normal repair functions resulting in a lower DNA repair capacity and an increase in the probability of developing noise-induced hearing loss." (PMID 36203702, 2022).
Hepatic fibrosis (2 papers, 2015 to 2020). The presence of excessive fibrous connective tissue in the liver. "In our study, XRCC1 rs25487 was demonstrated to be a strong prognostic factor for liver cirrhosis and advanced liver fibrosis." (PMID 33171788, 2020). "Interestingly, our results showed that XRCC1 KD leads to a proteomics profile much reminiscent of inflammatory events in hepatic fibrosis (rank 1)." (PMID 25800737, 2015). "As XRCC1 is one of the main players in the repair of ROS-induced lesions, it brings us to the conclusion that affecting protein function rs25487 may have an impact on HBV-induced liver fibrosis development." (PMID 33171788, 2020).
Insulin resistance (2 papers, 2018 to 2019). Increased resistance towards insulin, that is, diminished effectiveness of insulin in reducing blood glucose levels. "Therefore, the second objective of our study was to investigate the XRCC1 gene variants influencing the susceptibility of HCC related to HCV infection in the Egyptian population and to link it to the state of insulin resistance." (PMID 30366460, 2018).
liver cirrhosis (2 papers, 2020 to 2022). "The obtained results have demonstrated that SNPs within XRCC1, ERCC2 genes may confer susceptibility to liver cirrhosis in chronic hepatitis B patients." (PMID 33171788, 2020). "Even so, both studies present the same hypothesis that XRCC1 399 codon has an impact on development of HBV-induced liver cirrhosis." (PMID 33171788, 2020). "In conclusion, this study shows that functional and potentially functional SNPs within XRCC1 and ERCC2 genes may confer susceptibility to HBV-associated liver cirrhosis." (PMID 33171788, 2020).
lymphoma (2 papers, 2023). A malignant (clonal) proliferation of B- lymphocytes or T- lymphocytes which involves the lymph nodes, bone marrow and/or extranodal sites. "Interestingly, RNA-seq data from CAG-A3B lymphomas indicate positive associations between APOBEC mutation signature enrichment scores and mRNA levels for Ung2, AP endonuclease 1 (Apex1), and X-ray repair cross-complementing protein 1 (Xrcc1) but not for Rev1." (PMID 37797615, 2023). "An analysis of the mRNA levels of uracil excision repair factors in CAG-A3B lymphomas indicates positive associations between APOBEC signature enrichment and uracil DNA glycosylase 2 (Ung2), AP endonuclease 1 (Apex1), and X-ray repair cross-complementing protein 1 (Xrcc1), but not with Rev1." (PMID 36865194, 2023).
metastatic colorectal cancer (2 papers, 2009 to 2013). "A 5-fold greater incidence of failure by 5-FU/oxaliplatin therapy had been reported for metastatic colorectal cancer patients with XRCC1 R399Q (QQ or QR) substitution compared with that of the RR genotype, suggesting that the polymorphism was associated with resistance to oxaliplatin/5-FU therapy." (PMID 23990873, 2013).
Obesity (2 papers, 2024). Accumulation of substantial excess body fat. "The upregulation of XRCC1 and Ligase III in B-DNA mice on the obesity-inducing diet and H-DNA mice on both diets, compared to B-DNA mice on the CD, further suggests that the repair of obesity- and H-DNA-induced DSBs is carried out through an error-prone MMEJ pathway." (PMID 39043652, 2024).
preeclampsia (2 papers, 2014 to 2024). Preeclampsia is a hypertensive disorder of pregnancy that is characterized by new-onset hypertension with proteinuria presenting after 20 weeks of gestation, and depending on mild or severe forms may initially present with severe headache, visual disturbances, and hyperreflexia. "Polymorphisms in DNA repair genes, such as APE1 and XRCC1, were closely linked to heightened risks of preeclampsia and preterm birth, underscoring the genetic component in risk assessment." (PMID 39484166, 2024). "In the present study we aimed to investigate the association between APEX1 Asp148Glu, XPD Lys751Gln, XRCC1 Arg399Gln and XRCC3 Thr241Met polymorphisms and the risk of preeclampsia in a Mexican population." (PMID 24619222, 2014).
rectal cancer (2 papers, 2008 to 2013). A primary or metastatic malignant neoplasm that affects the rectum. "In a study of stage II/III rectal cancer patients in Spain, patients with XRCC1 Arg/Arg had a greater probability of a positive response to chemoradiotherapy than those with XRCC1 Arg/Gln (OR = 4.18, 95% CI = 1.62–10.7)." (PMID 23894404, 2013).
renal carcinoma (2 papers, 2017 to 2024). A carcinoma arising from the epithelium of the renal parenchyma or the renal pelvis. "However, this study confirmed that SDF-1ɑ expression was downregulated and that XRCC1 expression was upregulated in renal cancer tissues by bioinformatics methods and integrated information from the TCGA database." (PMID 38337001, 2024).
urothelial carcinoma (2 papers, 2015 to 2016). A malignant neoplasm derived from the transitional epithelium of the urinary tract (urinary bladder, ureter, urethra, or renal pelvis). "At the same time, the “risky” ERCC6 1097Val allele increased the frequency of urothelial carcinoma recurrences and the XRCC1 399 A/A (Gln/Gln) genotype greatly reduced recurrence free survival of BCG treated patients." (PMID 26649138, 2016). "Associations between cigarette smoking status, 8-OHdG level, and urothelial carcinoma risk stratified by XRCC1 (Arg399Gln) genotypes, XRCC1 (Arg194Trp) genotypes, and XRCC1 haplotypes." (PMID 25938407, 2015). "The joint effects of 8-OHdG level and XRCC1 (Arg399Gln) genotypes, XRCC1 (Arg194Trp) genotypes, and XRCC1 haplotypes on urothelial carcinoma risk stratified by cigarette smoking status." (PMID 25938407, 2015). "The aim of this study was to examine the associations between the combined effects of urinary 8-Hydroxydeoxyguanine (8-OHdG) level and polymorphisms of XRCC1 Arg194Trp and XRCC1 Arg399Gln on the risk of urothelial carcinoma (UC)." (PMID 25938407, 2015).
Xeroderma pigmentosum complementation group D (2 papers, 2014 to 2017). Xeroderma pigmentosum complementation group D (XPD) is a subtype of xeroderma pigmentosum (XP; see this term), a rare photodermatosis predisposing to skin cancers. "The polymorphisms of genes encoding antioxidant enzymes, such as glutathione S transferase (GST), genes encoding DNA repair enzymes, such as xeroderma pigmentosum complementation group D (XPD) and X-ray cross-complementing group 1 (XRCC1) have been confirmed as associated with ARC susceptibility." (PMID 28253266, 2017). "The genetic polymorphisms of X-ray repair cross complementing group 1 (XRCC1), X-ray repair cross complementing group 3 (XRCC3), and xeroderma pigmentosum complementation group D (XPD) repair genes may lead to genetic instability and leukemogenesis." (PMID 24955348, 2014). "Among them, polymorphisms of X-ray repair cross complementing group 1 (XRCC1), X-ray repair cross complementing group 3 (XRCC3), and xeroderma pigmentosum complementation group D (XPD) have been studied extensively." (PMID 24955348, 2014). "Therefore, another robust topic in previous association analysis has concerned the DNA repair enzyme genes, such as xeroderma pigmentosum complementation group D (XPD), and X-ray cross-complementing group 1 (XRCC1)." (PMID 28253266, 2017).
Adrenocortical carcinoma (1 paper, 2024). "We assessed XRCC1 expression levels in different tumor stages of Adrenocortical carcinoma (ACC), BLCA, and LIHC." (PMID 38217545, 2024).
AIDS (1 paper, 2022). A syndrome resulting from the acquired deficiency of cellular immunity caused by the human immunodeficiency virus (HIV). "In conclusion, the present study suggests that the polymorphisms of APEX1 and XRCC1 may increase the risk of HIV-1 susceptibility and the clinical progression of AIDS in MSM populations in northern China." (PMID 35368687, 2022). "In this study, we investigated whether seven potentially functional SNPs in the XRCC1 and APEX1 genes are associated with susceptibility to HIV-1 infection and the AIDS progression in men who have sex with men (MSM) populations in northern China." (PMID 35368687, 2022). "However, the roles of single nucleotide polymorphisms (SNPs) in APEX1 and XRCC1 and their impact on HIV-1 infection and AIDS progression remain unclear." (PMID 35368687, 2022).
and neck cancer (1 paper, 2021). "Previous studies have revealed that high XRCC1 expression levels are associated with resistance to radiotherapy in patients with lung, head, and neck cancer." (PMID 34094945, 2021).
autoimmune disease (1 paper, 2014). A disorder resulting from loss of function or tissue destruction of an organ or multiple organs, arising from humoral or cellular immune responses of the individual to their own tissue constituents. "Although there are several reports about the correlation between XRCC1 gene polymorphisms and autoimmune diseases such as rheumatoid arthritis and SLE, data on allelic variation of XRCC1 gene polymorphisms in SLE patients are limited." (PMID 24971336, 2014). "Although several evidences have shown the association between polymorphisms of XRCC1 gene and autoimmune diseases, there are few published reports about the association between XRCC1 Arg399Gln and Arg149Trp polymorphisms and SLE." (PMID 24971336, 2014).
biliary tract cancer (1 paper, 2017). "A recent publication showed that vascular invasion was significantly more frequent in patients with biliary tract cancers with a low expression of XRCC1." (PMID 29312615, 2017).
Bloom syndrome (1 paper, 2020). Bloom syndrome (BSyn) is a rare chromosomal breakage syndrome characterized by a marked genetic instability associated with pre- and postnatal growth retardation, facial sun-sensitive telangiectatic erythema, increased susceptibility to infections, and predisposition to cancer. "Our data report that the number of 100 SCEs per cell was nearly similar in degree to cells observed from Bloom syndrome and XRCC1-mutated CHO EM9 cells." (PMID 32927807, 2020).
Breast Invasive Carcinoma (1 paper, 2019). "The TCGA Breast Invasive Carcinoma dataset was analyzed using the UALCAN data portal for XRCC1 expression." (PMID 31596905, 2019). "So we evaluated XRCC1 expression in the TCGA Breast Invasive Carcinoma dataset using the UALCAN data portal." (PMID 31596905, 2019).
Cerebral ischemia (1 paper, 2024). Restriction of arterial blood supply to the brain associated with insufficient oxygenation to support the metabolic requirements of the tissue. "In cerebral ischemia models, MMP-2 cleaves PARP1 and XRCC1, two DNA repair enzymes, in vitro and in vivo to induce neuronal apoptosis." (PMID 39569367, 2024).
chronic cholecystitis (1 paper, 2020). "The epithelium of chronic cholecystitis with high XRCC1 expression showed moderate to severe dysplasia." (PMID 32426369, 2020). "Furthermore, we found that the epithelium of chronic cholecystitis with high XRCC1 expression showed moderate to severe dysplasia, suggesting that XRCC1 may be involved in the processes that benign lesions evolve into GBC." (PMID 32426369, 2020).
chronic kidney disease (1 paper, 2023). Impairment of the renal function secondary to chronic kidney damage persisting for three or more months. "Intriguingly, XRCC1, as an indicator of DNA damage, was highly expressed in chronic kidney disease." (PMID 37773127, 2023).
chronic lymphocytic leukemia (1 paper, 2025). "In chronic lymphocytic leukemia (CLL), Nrf2 activation can enhance the expression of DNA repair genes such as XRCC1 and POLB, which may contribute to disease progression and resistance to chemotherapy." (PMID 40422216, 2025).
Cirrhosis (1 paper, 2020). A chronic disorder of the liver in which liver tissue becomes scarred and is partially replaced by regenerative nodules and fibrotic tissue resulting in loss of liver function. "After adjusting for sex and age, logistic regression analysis showed that CHB individuals carrying the rs238406 G allele (ERCC2) and rs25487 T allele (XRCC1) are at increased risk of developing cirrhosis and liver failure." (PMID 33171788, 2020). "The homozygous TT genotype at ERCC2 rs238406, CC at XRCC1 rs25487, and GG at NBN rs2735383 were significantly associated with a lower risk of cirrhosis." (PMID 33171788, 2020). "We showed that SNPs within XRCC1 and ERCC2 genes are independently associated with increased risk of cirrhosis." (PMID 33171788, 2020).
colon adenoma (1 paper, 2008). An adenoma that arises from the colon. "The smoking has an effect on colon adenoma risks among carriers of XRCC1 codon 399 Arg alleles." (PMID 18823566, 2008).